INS (insulin)
Diseases named in the same sentence as INS in open-access papers (continued):
Sharing a sentence is not in itself a finding about the gene and the disease.
Insulin resistance (continued). "In type 1 diabetes, the insulin-producing cells of pancreatic islet are destroyed by the immune system, whereas type 2 diabetes is caused by a combination of insulin resistance and inadequate insulin secretion." (PMID 26082830, 2015). "FGF21-KO mice exhibited insulin resistance while being normoglycemic, associated with increases in beta-cell proliferation and insulin synthesis, acting as compensatory responses." (PMID 25811804, 2015). "The candidate genes under the chromosome 9 locus are likely to affect hepatic TG content via an insulin-dependent manner as the peak of association was diminished by co-mapping with obesity or insulin resistance." (PMID 26067236, 2015). "GDM has common features with type 2 diabetes mellitus; there are similar risk factors, mechanisms (i.e. insulin resistance and impaired insulin secretion) and genetic susceptibility for the both disorders." (PMID 26494989, 2015). "In early stage breast cancer survivors, high blood insulin levels, indicative of insulin resistance, are associated with obesity, poor lipid profiles, distant recurrence and death." (PMID 26339243, 2015). "Though insulin resistance has been proposed as one of the causes of this poor glycemic control, the role of adjunctive metformin, an insulin sensitizer, on glycemic control in these patients is unclear." (PMID 26367281, 2015). "Excess amounts of free fatty acids in the blood leads to JNK activation in tissues like the liver, and causes insulin resistance through inhibition of the insulin-signaling pathway." (PMID 26024298, 2015). "In type 2 diabetes, insulin clearance is impaired and is associated with insulin resistance and the loss of beta cell mass." (PMID 25822220, 2015). "Recently we reported that both decreased insulin secretion and increased insulin resistance were associated with the development of type 2 diabetes in participants of the METSIM study." (PMID 26561346, 2015). "Insulin-resistant individuals, particularly those whose insulin resistance is associated with central adiposity, display blunted sympathetic neuronal responses to physiological hyperinsulinemia, glucose consumption, and changes in energy states." (PMID 26064978, 2015). "Although several lines of evidence both in human studies and animal models indicate that ABCA1 plays a role in insulin secretion and insulin resistance, the role of ABCA1 gene variation in T2D susceptibility and insulin resistance is not fully understood." (PMID 26579206, 2015). "Aging is a risk factor for insulin resistance, and insulin signaling decrease is believed to be the cause that triggers the neurodegenerative processes, particularly in AD." (PMID 25889938, 2015). "Insulin resistance and defective insulin secretion are the two leading pathological causes in type 2 diabetes." (PMID 25999625, 2015). "Insulin resistance can occur due to interference in the common insulin signalling cascade due to either genetic mutations or structural modifications to any of the signalling nodes in the insulin signalling pathway." (PMID 26693205, 2015). "Overall, our findings indicate that Cidea is highly associated with adiposity and insulin resistance, whereas Cidec is related to insulin sensitivity." (PMID 26176546, 2015). "We previously identified that this miR is positively associated with insulin resistance and response to thiazolidenidones, which improve insulin sensitivity, in a multiracial sample." (PMID 26966540, 2015). "Mif deficiency protects against development insulin resistance: fasting plasma glucose and insulin lower, improved ipGTT, ipITT, and euglycemic clamp." (PMID 26124760, 2015). "Even in control children, maternal insulin concentrations were associated positively with offspring subscapular skinfold thickness and homeostasis model assessment for insulin resistance (HOMA-IR)." (PMID 25478935, 2015).
Insulin resistance (continued). "The increased insulin production caused by insulin resistance in T2DM leads to chronic ER stress and this contributes to the death of β-cells by apoptosis." (PMID 26426397, 2015). "Adequate insulin action in the brain has been linked to a lean and healthy phenotype while insulin resistance in the brain is associated with obesity, glucose intolerance, physical inactivity and even Alzheimer ́s disease." (PMID 25965336, 2015). "Glucose clearance during an OGTT at week 18 was not different between B6-WT and B6-Tg(Zfp69) mice, but the insulin concentration was significantly increased in B6-Tg(Zfp69) mice, suggesting that Zfp69 overexpression causes mild insulin resistance." (PMID 26232096, 2015). "BDE-47 treatment in early life induces insulin resistance in susceptible mice with intrinsic sensitivity to insulin." (PMID 26217518, 2015). "Higher BMI values were associated in EC patients with an increase in fasting serum insulin level and insulin resistance index." (PMID 28031919, 2015). "In fact, the perceived role of this phenomenon is the reason why therapeutic approaches to the management of insulin resistance and other associated cardiometabolic diseases involve the use of agents that promote insulin signaling." (PMID 26273674, 2015). "Chronic low-grade inflammation in adipose tissue impairs insulin signalling, which further stimulates expression of genes encoding proteins implicated in insulin resistance." (PMID 26110385, 2015). "This study examines the association RHR and physical activity has with insulin resistance and insulin secretion in a multiethnic cohort from North Kohala, Hawai‘i." (PMID 25973404, 2015). "Since glucocorticoid-induced insulin resistance is generally associated with an increase of endogenous insulin, we determined the plasma insulin level of mice treated with various doses of VSGC12 and FF." (PMID 27066265, 2015). "Recent studies have demonstrated that ENPP1 affects both the function and survival of pancreatic beta cells, thus representing a strong pathogenic factor predisposing to insulin resistance, defective insulin secretion, and impaired glucose metabolism." (PMID 26302420, 2015). "A key mediator of the beneficial effect of weight loss on insulin sensitivity is the loss of ectopic fat, which is highly correlated to insulin resistance and T2DM." (PMID 26500686, 2015). "Insulin-sensitizing agents have been explored for treating the underlying cause of disorders associated with insulin resistance." (PMID 25653680, 2015). "Adiponectin has shown to enhance insulin sensitivity, and its decreased production is associated with insulin resistance." (PMID 26492243, 2015). "The positive correlation between ENC1 expression and ERK phosphorylation in response to insulin suggests a possible mechanism for higher cancer risk in patients with insulin resistance." (PMID 26202599, 2015). "According to the World Health Organization, diabetes is a syndrome characterized by hyperglycemia with disturbances in protein, lipid, and carbohydrate metabolism due to a deficiency in insulin production (in T1D) or insulin resistance (in T2D)." (PMID 26500652, 2015). "In the offspring group, decreased GM MTR peak height, an index of microstructural brain parenchymal homogeneity was significantly associated with higher indices of insulin resistance (fasted insulin, AUCinsulin and HOMA-IR, all p < 0.01)." (PMID 26074813, 2015). "Insulin resistance associated with s.c. insulin administration is another uncommon condition that complicates T1DM management." (PMID 24711924, 2014). "Concurrently, obesity associated hepatic insulin resistance dampens the repression of VLDL-TG secretion normally observed in the presence of hepatic insulin sensitivity." (PMID 25061524, 2014).
Insulin resistance (continued). "Insulin resistance, defined as an impaired biological response to either exogenously or endogenously derived insulin, can impair insulin action on insulin-sensitive target organs and cause impaired glucose tolerance as seen in DM." (PMID 25024728, 2014). "TNF-α seems to play a role in the physiopathology of blood hypertension (BHP) associated with obesity and insulin resistance, as it inhibits insulin dependent glucose uptake by interfering with its signaling." (PMID 24741627, 2014). "The macro elements such as calcium and magnesium have been associated with impaired insulin release, insulin resistance, and glucose intolerance in experimental animals and humans." (PMID 25162051, 2014). "Type 2 diabetes is a metabolic disorder caused by insulin resistance and relative reduction of insulin production." (PMID 24910800, 2014). "The rare allele A carriers had higher insulin concentration and insulin resistance than G/G homozygote carriers." (PMID 24665145, 2014). "TNF-α was the first cytokine associated with insulin resistance in animals; it is overexpressed in adipose tissue in obesity and decreases with weight loss, being also considered as an important insulin resistance regulator." (PMID 24741627, 2014). "A glycine-to-arginine substitution in codon 972 (Gly972Arg) of the IRS-1 gene (rs1801278) has been shown to be associated with a high prevalence of T2DM and GDM due to insulin resistance and impaired insulin secretion." (PMID 24695443, 2014). "In the brain, insulin resistance results from perturbation of insulin signal transduction, causing systemic hyperglycemia." (PMID 24860814, 2014). "Length of stay was associated with C-peptide, insulin, and blood glucose levels, insulin resistance, and severity of illness at 24 hours." (PMID 24628829, 2014). "Of them hyperinsulinaemia caused by insulin resistance, increased cholesterol saturation index in bile due to the stimulatory effect of insulin on HMG Co A reductase (3-hydroxy-3-methyl-glutaryl-CoA reductase) enzyme are discussed widely." (PMID 24884475, 2014). "The HFD/STZ mouse model manifested hyperglycemia and hyperlipidemia associated with insulin resistance and impaired insulin secretion, as described in previous reports." (PMID 24968071, 2014). "BMI, WC and WHR associated positively with triglycerides, fasting insulin and Homeostasis Model Assessment of Insulin Resistance index." (PMID 25147770, 2014). "In contrast to the oncogenic hyper-activation of the PI3K/Akt/mTOR pathway, it is the hypo-activation of this pathway that attenuates cellular insulin response, causing insulin resistance and even T2D." (PMID 25334061, 2014). "The elevation in cytokine levels causes systemic insulin resistance by reducing the efficiency of the insulin signalling cascade in peripheral tissues." (PMID 24740015, 2014). "In our experience, there is a widely held perception that liver steatosis is associated with increased production of insulin from the beta-cell in order to compensate for whole-body insulin resistance." (PMID 24669786, 2014). "The intake of a Mg-deficient high-fat diet led to alterations in the insulin-signaling pathway and consequently increased insulin resistance." (PMID 25013896, 2014). "Resistin injection in rodent causes insulin resistance whereas with antibodies against resistin increased the insulin sensitivity in obese mice." (PMID 24695544, 2014). "Some studies have suggested that large fat cells are less responsive to insulin, pointing to mature hypertrophic adipocytes as one of the causes of insulin resistance." (PMID 24751908, 2014). "First, chronic exposure to excess insulin (glargine) caused insulin resistance, hyperinsulinemia, and relative insulin insufficiency." (PMID 24741073, 2014). "Insulin resistance can develop over time in patients with metabolic diseases due to acute attacks or to deficiency in insulin reserves in the pancreas." (PMID 24637313, 2014).
Insulin resistance (continued). "Numerous studies have demonstrated that impaired insulin signaling is closely associated with insulin resistance concomitant with obesity and type 2 diabetes." (PMID 25398386, 2014). "It is known that LVDD is associated with insulin resistance and a deleterious action of insulin on this parameter and on the development of cardiovascular disease has been suggested." (PMID 25285158, 2014). "Insulin resistance is common to both obesity and type 2 diabetes, and apelin is linked with obesity-associated variations of insulin sensitivity status." (PMID 24475149, 2014). "Decreased adiponectin levels have been consistently associated with impaired insulin signaling and insulin resistance and increased cardiovascular risk." (PMID 24527033, 2014). "To test the basic premise of this study, i.e. does a loss of AMPD activity alter insulin resistance, we examined blood glucose and insulin levels in wild-type and A1(−/−) mice fed a standard chow diet (CD) and a high fat diet (HFD)." (PMID 25511531, 2014). "Albeit still controversial, evidence is accumulating that also in humans β-cell number increases under conditions associated with increased insulin demand such as obesity, pregnancy and insulin resistance, and decreases in longstanding T2D." (PMID 24905913, 2014). "Other studies showed that insulin resistance induced by inflammation is associated with insulin signaling events downstream of the IR." (PMID 25259572, 2014). "Adiponectin influences carbohydrate metabolism, improving insulin sensitivity, and low adiponectin levels have been suggested to play a causal role in the development of insulin resistance and cardiovascular disease in adulthood." (PMID 25045669, 2014). "Hepatic steatosis was also shown to occur in human populations with postreceptor mutations in the insulin signaling pathway leading to insulin resistance." (PMID 25371775, 2014). "Phosphatidylinositol 3-kinase plays an important role in the metabolic actions of insulin, and a mutation in this gene has been associated with insulin resistance." (PMID 25057111, 2014). "Curiously, however, relatively high neurogenesis was positively associated with adolescent biomarkers indicative of insulin resistance, including plasma insulin, insulin/glucose ratio, and HOMA-IR." (PMID 25506432, 2014). "Both factors contribute to insulin resistance and loss of β-cell function, leading to impairment in insulin action, insulin production, or both." (PMID 24616740, 2014). "Insulin resistance, as estimated by fasting insulin and the HOMA index, was inversely associated with exercise capacity in patients with type 2 diabetes and CAD, the association being more pronounced in the subgroup with exercise-induced ischemia." (PMID 24612649, 2014). "Regression models confirmed a strong association between risk of insulin resistance, T2D and age with both fasting insulin levels (0.12 pmol/l per year) and risk of T2D [odds ratio (OR) = 1.04 per year] increasing with age." (PMID 25117150, 2014). "This would raise the threshold of insulin response, and the resulting insulin resistance would increase the risk of T2D." (PMID 25334061, 2014). "Other studies have shown that TNF-α causes cardiac insulin resistance by inducing degradation of insulin receptor substrate protein 1, which is critical for cardiac insulin signaling." (PMID 24521405, 2014). "The result of this study also showed that there was an association between current smoking status and insulin sensitivity and insulin resistance." (PMID 24416185, 2014). "Although mechanisms are unclear, disruption of insulin signaling is strongly suggested, in particular insulin resistance or deficiency in the brain." (PMID 24764191, 2014). "The association of fasting plasma glucose, insulin, and biguanide use with the presence of hepatic lipid is concordant with previous studies identifying insulin resistance/type 2 diabetes as a risk factor." (PMID 25610640, 2014).
Insulin resistance (continued). "A deficiency of adiponectin in mice induces insulin resistance, whereas over-expression of adiponectin in mice improves insulin sensitivity and glucose tolerance." (PMID 24733068, 2014). "Proinflammatory M1 macrophages induce an inflammatory state and insulin resistance through inhibition of insulin signaling caused by IL-6 and TNF-alpha." (PMID 24741627, 2014). "In this study, we addressed this issue and found that chronic exposure to excess insulin caused insulin resistance, hyperinsulinemia, and relative insulin deficiency, i.e., T2DM, in mice fed on a chow diet." (PMID 24741073, 2014). "In recent GWAS studies, variants at or near TCERG1L have been associated with fasting insulin, insulin resistance and attention deficit disorder." (PMID 24499112, 2014). "These are all desirable traits because increased fat mass are associated with decreased insulin sensitivity and increased morbidity and mortality, furthermore, visceral fat is causally associated with insulin resistance." (PMID 24498905, 2014). "The role of amylin in the pathogenesis of T2D has been suggested by in vitro and in vivo studies indicating its effect to cause insulin resistance and/or inhibit insulin secretion." (PMID 25141237, 2014). "They found that FABP2 Ala54Thr polymorphism was weakly associated with a higher degree of insulin resistance, higher level of fasting insulin and higher level of 2-h BG." (PMID 25388378, 2014). "The central features of T2DM are a defect in insulin resistance and/or insulin secretion, which lead to hyperglycaemia; disruption of the normal relationship between insulin sensitivity and pancreatic β-cell function is a hallmark of T2DM progression." (PMID 24650557, 2014). "Saturated fatty acids cause insulin resistance and reduce insulin production in the pancreatic islets, thereby generating a vicious cycle, which potentially culminates in type 2 diabetes." (PMID 24896641, 2014). "The purpose of the present study was, therefore, to examine the regulation of the onset of muscle differentiation by high glucose combined with high insulin, one of humoral factors associated with insulin resistance and obesity." (PMID 24615360, 2014). "A correlation relationship between low plasma insulin concentration and reduced mortality risk and lower insulin resistance is also observed in humans." (PMID 24474199, 2014). "A growing body of evidence indicates that obesity causes hepatic insulin resistance, leading to impaired regulation of glycogenolysis and gluconeogenesis by insulin, thereby increasing hepatic glucose production and output." (PMID 25147566, 2014). "Adiponectin levels are inversely proportional to obesity and insulin resistance, increasing with weight loss and with the use of insulin-sensitizing drugs." (PMID 24741591, 2014). "In fact, free radicals act as a double-edged sword in modulating insulin signaling, being required for insulin to exert its physiological action, but also being implicated in the pathogenesis of insulin resistance." (PMID 24905823, 2014). "It has been proposed that the accumulation of lipids in the muscle cell should interfere with insulin signaling, thereby causing insulin resistance." (PMID 25601841, 2014). "The synthesis of apelin in adipocytes is triggered by insulin and its plasma levels are reported to increase in association with insulin resistance and hyperinsulinemia." (PMID 24475149, 2014). "Intramyocellular lipid levels are inversely associated with insulin sensitivity, and an increase in skeletal muscle TG content due to hypertriglyceridemia exacerbates insulin resistance." (PMID 25360162, 2014). "Studies have shown extensive association between oxidative stress markers and obesity, insulin resistance, and diabetes through interference of insulin signaling." (PMID 24789994, 2014).